HOXA10-AS (HOXA10 antisense RNA)
Synonyms: HOXA-AS4
Gene: Long non-coding RNA gene on chromosome 7 (27,166,151 to 27,172,207, forward strand). Ensembl gene ENSG00000253187.
Gene Ontology:
Biological process: miRNA-mediated post-transcriptional gene silencing
Cellular component: RISC complex